TNF (tumor necrosis factor)
Diseases named in the same sentence as TNF in open-access papers (continued):
Sharing a sentence is not in itself a finding about the gene and the disease.
diabetes (continued). "The treatment of the STZ-induced diabetes with the bovine extract showed an improvement of 76.77% and 41.82% for TNF-α and IL-6, respectively, while the improvement with the sheep extract reached 73.74 and 95.45%, respectively." (PMID 37764820, 2023). "On the other hand, when adjusting for age, sex, hypertension, diabetes mellitus, ALT, AST, GGT, creatinine, and uric acid (Model 2), only IL-6, IL-10, TNF, and IP-10 levels remained significantly associated with AF." (PMID 36834735, 2023). "Diabetes mellitus exhibited an inflammatory basis with increased tumor necrosis factor α (TNF-α), a pleiotropic cytokine playing a critical role in the inflammatory process and disease progression." (PMID 37373315, 2023). "When SGLT2 inhibitors were provided, the same group showed diabetes-associated increases in inflammation-suppressed NLRP3 inflammasome activity as well as lower mRNA levels of ASC, IL-6, IL-1b, TNF-a, and caspase-1." (PMID 37566054, 2023). "In the present study, we investigated the effect of various diabetes-associated mechanisms such as high-glucose, the hypoxia mimetic agent CoCl2, VEGF and the proinflammatory cytokine TNF-α on the expression of membrane-bound CD40 and sCD40." (PMID 37958563, 2023). "The periapical inflammation of LPS-induced apical periodontitis in diabetes mellitus rats increased macrophages' expression of IL-6 at 42 days and TNF-a at 28 days." (PMID 36599453, 2023). "Recent meta-analysis including more than 20 studies has shown a significant increase in blood serum TNF-α levels in people with diabetes." (PMID 37627482, 2023). "Regarding diabetes, it has been reported that inflammatory factors such as TNF-α, IL-1ß, IL-6, and IL-18 are increased in diabetic patients, contributing to insulin resistance through the JNK and IKKb/ NFkB pathways." (PMID 36832168, 2023). "Prolonged enhanced concentrations of the pro‐inflammatory cytokines IL‐1β and TNFα in blood, and reduced anti‐inflammatory IL‐10 in sputum, have been observed in patients with TB and diabetes comorbidity, in accordance with our results." (PMID 37649224, 2023). "Fructose/STZ-induced diabetes resulted in a significant increase in TNF-α (P < 0.001) and INF-γ (P < 0.01) levels in diabetic control compared to normal control." (PMID 37441190, 2023). "An in vitro study showed that targeted overexpression of TNF-α in pancreatic cells of transgenic mice augmented the progression of diabetes." (PMID 37189738, 2023). "Diabetes also enhances Foxo1 DNA binding to TNF-α and RANKL promoters and increases their expression in diabetic fracture calluses." (PMID 37591875, 2023). "Previous studies have shown the detrimental effects of TNF-α on glucose and lipid metabolism as well as its involvement in β-cell apoptosis and endothelial dysfunction in diabetes." (PMID 37168278, 2023). "Previous studies have shown that luteolin inhibits high-glucose-induced activation of NF-κB in human monocytes and the release of the proinflammatory factor TNF-α, with potential preventive and therapeutic activity in diabetes mellitus." (PMID 36820318, 2023). "The logistic regression analysis revealed a statistically significant relationship between diabetes and age, low Vit D levels, high TNF-α and high MAPK levels." (PMID 38136648, 2023). "Possibly, the activation of TLR4 in the Schwann cells and spinal cord of diabetics induces an overproduction of TNF-α, resulting in the increase of pain." (PMID 36946851, 2023). "Many studies have reported the efficacy of moringa and ginger in type 2 diabetes mellitus, neurodegenerative disease, cardiovascular disease, cancer, and kidney disease by reducing inflammatory cytokines activities, mainly of TNF-α and IL-6." (PMID 37570837, 2023). "Allium Sativum plays a role in the treatment of diabetes by enhancing the gene expression of caspase 3 and caspase 9, reducing IL-1β, IL-6, and TNF-α level and increasing IFN-γ in vitro and in vivo." (PMID 37240430, 2023).
diabetes (continued). "Diabetes itself leads to increased cytokine production, including interleukin (IL)-1, IL-6, IL-8, and tumor necrosis factor-α (TNF-α)." (PMID 37834356, 2023). "The sustained diabetes-evoked inflammatory responses mediated by pro-inflammatory modulators (IL-1β, TNF-α) majorly contribute to the development of DR, consequently altering the retinal structure and impairing its function." (PMID 37032781, 2023). "The impact of diabetes was directly related to the level of inflammation as inhibition of TNF rescued this effect." (PMID 37576976, 2023). "Comorbidities, such as hypertension and diabetes, can also affect the production of pro-inflammatory cytokines including IL-2R, IL-10 and TNF-α." (PMID 37969879, 2023). "The COL-1, COL-2, TNF-α mRNA expression in trigger fingers with diabetes, hypertension and dyslipidaemia was significantly increased compared to the TF group." (PMID 37853419, 2023). "In rats with streptozotocin-induced diabetes, there was an increase in levels of the NF-kB protein and TNF-α." (PMID 37371821, 2023). "Previous studies have revealed that HMGB1 inhibitor GA treatment protects against kidney lesions induced by diabetes, which is related to the reduced expression of TNF-α, 1L-6, IL-1β, MCP-1, and ICAM-1 in the kidney." (PMID 35578754, 2022). "Many studies have demonstrated that diabetes can increase the levels of human pro-inflammatory factors, such as TNF-α, IL-1β, and IL-6." (PMID 35813617, 2022). "Pro-inflammatory cytokines, especially TNF-α, can lead to cardiac remodeling and dysfunction in the progression of diabetes." (PMID 36187088, 2022). "Diabetes occurs in part because the accumulation of triggered innate immune cells leads to the release of inflammatory markers, principally IL-1β and tumor necrosis factor α, that promote generalized resistance to insulin and destruction of β-cell." (PMID 35975270, 2022). "Blocking both IFN-γ and TNF-α significantly delayed the development of diabetes (median time = undef versus 14 days, P = 0.006)." (PMID 35925682, 2022). "Regarding biochemical parameters, in addition to glucose, which was expected to be higher in subjects with diabetes, the “Diabetic” group also presented higher values of triglycerides, systolic blood pressure, IL-6, and TNF-α." (PMID 35336365, 2022). "Earlier, our group has reported that a TNF-α inhibitor (MDL 201.449A) prevented the development of diabetes in MLDSTZ mice." (PMID 35887317, 2022). "This study aimed to analyze the reduction of tumor necrosis factor-α (TNF-α) in diabetics who came for periodontitis examination to prevent exacerbations." (PMID 35016229, 2022). "HCK plays a vital role in the macrophage activation and the secretion of TNF-α, which leads to the progression of diabetes." (PMID 36568106, 2022). "A report has indicated that the overexpression of miR-342-3p following inhibition of NEAT1 decreases the release of the inflammatory cytokines IL-6, IL-1β, TNF-α, and cyclooxygenase-2 in type 1 diabetes mellitus." (PMID 36310619, 2022). "SGLT-2 inhibitors can reduce inflammatory markers such as interleukin-6 (IL-6), monocyte chemoattractant protein-1 (MCP-1), and tumor necrosis factor (TNF-α), thereby alleviating arteriosclerosis in diabetes animal models." (PMID 35676606, 2022). "Studies have displayed that DNA methylation in the promoter region alters the expression of TNF-α and other genes in visceral adipose tissue of Uyghur patients with diabetes." (PMID 35433838, 2022). "Early studies have reported the link between OPTN expression and the progression of diabetes, wherein its expression can be induced by TNF-α and interferons." (PMID 36551820, 2022). "AM1710 attenuated the diabetes-induced increase in the number of reactive Iba1+ cells as well as the levels of TNFα in diabetic retinas, in a statistically significant manner." (PMID 36613692, 2022).
diabetes (continued). "In bDMARD-naïve RA patients, abatacept showed a lower risk of cardiovascular events than TNF inhibitors in specific subgroups with a history of CVD, type 2 diabetes mellitus, and in elderly patients (age ≥ 65 years)." (PMID 36430392, 2022). "AM1710, reduced the diabetes induced elevated levels of TNFα (AM1710: n = 6, 408.00 ± 70.09, #p = 0.0290 compared to Diabetic untreated)." (PMID 36613692, 2022). "Naringin exhibit its neuroprotective impact by downregulation of free radical, cytokine including TNF-α thus preventing diabetes-induced neuropathic pain over modulation of endogenous biomarkers." (PMID 36249455, 2022). "In another ex vivo study, the number of osteoclasts expressing IL-6 and TNF-α was elevated in bone specimens from diabetes patients suffering from CN." (PMID 36499493, 2022). "No statistical differences were found in the age, genders, duration of diabetes, concomitant risk factors, BMI, FPG, 2h-PBG, HbA1c, TC, TG, SCr, BUN, TNF-α, IL-6, and hs-CRP between both the groups (P > 0.05)." (PMID 36177313, 2022). "Other risk factors for abdominal TB are human immunodeficiency virus (HIV) infection, malnutrition, diabetes mellitus, malignancy, liver cirrhosis, peritoneal dialysis, and certain biologics including tumor necrosis factor-alpha (TNF-α) inhibitors." (PMID 34613520, 2022). "Experimental evidence illustrated that HLF treatment significantly downregulates the overexpression of NF-κBp65 and TNF-α in cardiac tissue after induction of diabetes." (PMID 35711333, 2022). "Patients with diabetes mellitus are in a prolonged chronic inflammatory state, and there is prolific activation of inflammatory cytokines, including tumor necrosis factor α (TNF-α) and interleukin 6 (IL6)." (PMID 36589835, 2022). "More importantly, the mechanisms of how adiponectin, nesfatin-1, TNF-α, and IL-6 are involved in the progression of prediabetes toward diabetes are worth our in-depth exploration." (PMID 35311231, 2022). "STZ- and high-fat diet-induced diabetes also demonstrated abnormal immune responses in the colon with the increased levels of colonic IL-β and TNF-α and the RPE decreasing these parameters." (PMID 35741945, 2022). "First, TNF‐α, IL‐6, IL‐1β, and IL‐18 are known to be key influential modulators of diabetes, as also cytokines which are upregulated during the systemic immune response to stroke." (PMID 35971650, 2022). "SARS-CoV-2 infection leads to increased levels of inflammatory cytokines such as TNF-α, IL-1, and IL-6, which are also increased in diabetes." (PMID 36079032, 2022). "For islet vascular damage in diabetes, neutrophil transmigration across TNF-activated endothelial monolayers can be accelerated by co-clustering L-selectin with PECAM-1." (PMID 36527108, 2022). "The plasma levels of some cytokines including interleukin (IL)-1β, interferon (IFN)-γ, and tumor necrosis factor α (TNFα) increase significantly in patients with diabetes (King, 2008 ▶)." (PMID 35145896, 2022). "Previous reports indicated that persistent hyperglycemia was closely associated with a pro-inflammatory status, characterised by a significant elevation of IL-1β, IL-6, -1B and -8 and TNF-α in patients with uncontrolled diabetes and ketoacidosis." (PMID 35327652, 2022). "Increased serum levels of TNF-α have been accompanied by diabetes development, as it is known to interfere with signal transduction mediated by insulin receptor that leads to the inhibition of the insulin effect." (PMID 35335970, 2022). "In diabetes, renal cells (epithelial, mesangial, endothelial, and tubular cells) produce the cytokine of inflammatory IL-6 and TNF-α." (PMID 35685736, 2022). "Overall in patients with diabetes, an imbalance towards M1 macrophages increases expression of pro-inflammatory cytokines like TNF-α and decreases IL-10 production (r = −0.224, p = 0.004) by M2 cells, and delays wound healing." (PMID 35836916, 2022).
diabetes (continued). "As diabetes is linked to cytokine-mediated inflammation leading to loss of functional β-cell mass, we next asked whether treating islets with three key cytokines (TNFα, IFNγ, IL-1β, or a cocktail of all three) affects LIM-domain complex factor expression levels." (PMID 34968409, 2022). "For example, telomerase directly regulates NF-κB-dependent gene expression, such as that of IL6 and TNFα; cytokines were previously shown to be involved in the inflammatory pathogenetic pathways of the complications of diabetes and cancer." (PMID 35628895, 2022). "The pro-inflammatory markers TNF-α, IL-6 and insulin-like growth factor (IGF), associated with visceral adiposity and diabetes, are associated in vivo and in vitro models with HCC development and progression." (PMID 36145251, 2022). "In diabetes-associated atherosclerosis, the PDGF and TNF-α induced activation, increased proliferation, and migration of VSMCs are associated with decreased levels of let-7b and let-7d via Lin28b, a negative regulator of let-7 biogenesis." (PMID 36614057, 2022). "A complete blockade of TNF-α expression was found in the diabetes-induced model after the knockdown of TNF-α in macrophages." (PMID 36466094, 2022). "Zafirlukast has also been reported to prevent tamoxifen-induced oxidative stress and inflammation and TNF-αinduced endothelial inflammation; Bromocriptine has been reported to be used for glycemic control in patients with type 2 diabetes mellitus." (PMID 36378718, 2022). "Elevated levels of TNF-α and IL-1B have been revealed to increase cell apoptosis and decrease fibroblast proliferation, leading to impaired wound healing in diabetes." (PMID 36484062, 2022). "The major cytokine involved in carcinogenesis is TNF-α, which activates the NF-κB pathway, and similar inflammatory responses exist in gout, diabetes, and chronic kidney disease." (PMID 36139553, 2022). "In the pathogenesis of diabetes, inflammatory factors, such as interleukin (IL)-1β, IL-8, tumor necrosis factor (TNF)-α, and induced nitric oxide synthase (iNOS), are important factors related to insulin sensitivity." (PMID 35056765, 2022). "Mediators of inflammation—TNF-α, IL-1β, the IL-6 family of cytokines, IL-18, and certain chemokines—are believed to be involved in the etiology of diabetes." (PMID 35330193, 2022). "The induction of diabetes increased the levels of IL-1β, IL-6, and TNF-α in the DCM model, and these effects were inhibited by PQQ." (PMID 34997266, 2022). "On the other hand, IL-10/TNF-α, IL-10/IL-6, IL-10/IL-12, Gal-3/TNF-α, Gal-3/IL-6, and Gal-3/IL-12 (p = 0.001) were significantly higher (p < 0.05) in gonarthrosis with diabetes mellitus." (PMID 36141752, 2022). "Diabetes induction resulted in an increase in proinflammatory parameters TNF-α, IL-1β and IL-6, which were estimated using an ELISA technique in this study." (PMID 35335923, 2022). "It should be said that some inflammatory biomarkers such as TNF-α, interleukin 6 increase in diabetes." (PMID 36266683, 2022). "p75NTR-KO mice are protected from diabetes-induced retinal inflammation and show decreased TNF-α expression." (PMID 35309353, 2022). "It has been demonstrated that patients with diabetes tend to have a higher level of inflammatory cytokines, such as tumor necrosis factor α (TNF-α) and interleukin (IL-6)." (PMID 35631151, 2022). "Previously, we demonstrated that diabetes increases intestinal iNOS expression, NO levels in the portal vein, and IL-1β and TNF-α expressions in liver Kupffer cells." (PMID 35883204, 2022). "Diabetes induced the upregulation of serum TNF-α, IL-6, and IL-1β, and treatment with anti-ANGPTL3/IL22 showed prominent reversal compared with mIL22Fc or anti-ANGPTL3 alone." (PMID 36544775, 2022). "Diabetes aggravated adverse cardiac remodeling, increased the mortality rate, cardiac hypertrophy, the fibrotic area, and enhanced IL-1β, IL-6, TNF-α, and IL-18 expression in myocardial tissue." (PMID 36320147, 2022).
diabetes (continued). "One of the most common indicators of diabetes-induced inflammation is the release of tumor necrosis factor (TNF), interleukin 6, and decreased production of adiponectin (IR)." (PMID 36582387, 2022). "Early growth response 1 (Egr1) is another target gene of miR-150, and knockdown of this target alleviates the diabetes-induced inflammation in mouse mesangial cells by downregulating pro-inflammatory factors (IL-1β, IL-6, and TNF-α)." (PMID 36292956, 2022). "There are mechanistic links between periodontitis and other metabolic diseases, namely diabetes, which results in the production of inflammatory cytokines such as IL-1β, TNF, IL-6, as well as oxidative stress." (PMID 36013449, 2022). "The current results indicated that IHC reactions of IKK-i, IκBα, NF-κB, and TNF-α in kidney tissues changed after diabetes was induced." (PMID 35966750, 2022). "Our study confirmed that diabetes led to pyroptosis in rat cardiomyocytes and promoted an increase in the levels of the inflammatory factors NF-κB, IL-1, and TNF-α." (PMID 36624860, 2022). "NF-κB activation led to an increased level of inflammatory cytokines such as tumor necrosis factor-alpha (TNF-α), which led to cardiac complications in diabetes." (PMID 35888760, 2022). "From the literature evidence, it has been found that the levels of TNF-α significantly increase in an animal model of diabetes administered with STZ." (PMID 35795278, 2022). "Multiple studies have identified links between diabetes and inflammatory markers, such as tumor necrosis factor-α, interleukin-6, and C-reactive protein." (PMID 35971094, 2022). "Several pro-inflammatory markers, such as C-reactive protein, IL-1b, IL-6, IL-8, and TNF-α, are elevated in migraine and diabetes." (PMID 36498528, 2022). "RAM11, RAGE, and TNF-α expression were significantly lower in the Diabetes+Dapa group compared with the Diabetes group, and comparable to the Control group." (PMID 36068525, 2022). "Potential targets are mainly enriched in the AGE-RAGE signaling pathway in diabetes complications, lipids and atherosclerosis, fluid shear stress and atherosclerosis, IL-17 signaling pathway, TNF signaling pathway, and others." (PMID 36619785, 2022). "In the present study, the effect of endurance training on the expression of NLRP3, P38 MAPK, TNF-α, and IL-1β genes in the spinal cord of rats with diabetic neuropathic pain was investigated." (PMID 35655729, 2022). "After eight weeks of oral treatment of scutellarin (50 mg/kg), mice in the 35 mg/kg streptozotocin (STZ)-induced diabetic mouse model had enhanced learning and memory functions, and IL-β and TNF-α levels were reduced." (PMID 36678547, 2022). "HCK is important for macrophage activation and the TNF-α secretion, involved in diabetes progression." (PMID 36432612, 2022). "Overexpression of miR-93-5p in the diabetic retina alleviates the microvascular degeneration, downregulates pro-inflammatory factors (IL-1β, IL-6, and TNF-α), and elevates antioxidant levels, including GSH and superoxide dismutase (SOD)." (PMID 36292956, 2022). "Inflammatory markers, RAM11, RAGE, and TNF-α were significantly reduced in the Diabetes+Dapa group compared to those in the Diabetes group." (PMID 36068525, 2022). "Calycosin also can ameliorate diabetes-induced renal inflammation as indicated by the reduced TNF-α level." (PMID 35722158, 2022). "ROC analysis was used to identify cut-off values of ApoA1, IL-10 and TNF-α in diabetes patients with foot ulcers." (PMID 35836916, 2022). "At present, CRP, IL-6, and TNF-α are recognized as representative markers of inflammatory factors in patients with diabetes, which can damage EPCs’ function, and reduce endothelial regeneration and vascular repair." (PMID 36199064, 2022). "Secondly, the size of the participants in this study is relatively small, and more cases are required to verify the variations of adiponectin, nesfatin-1, TNF-α, and IL-6 in prediabetes and diabetes, as well as to make the conclusion more convincing." (PMID 35311231, 2022).